CDK9 (cyclin dependent kinase 9)
Diseases named in the same sentence as CDK9 in open-access papers (continued):
Sharing a sentence is not in itself a finding about the gene and the disease.
lymphoma (continued). "Cyclin-dependent kinase 9 (CDK9) regulates transcriptional elongation and activation of transcription factors, including MYC, making it a potential targeted approach for the treatment of MYC+ lymphomas." (PMID 37882668, 2023). "When cyclin-dependent kinase 9 (CDK9) inhibitors were applied to down-regulate both BFL-1 and MCL-1, an induction of apoptosis in BH3-mimetic–resistant lymphoma cells was observed, and regression of BFL-1+ DLBCL was achieved in patient-derived xenograft (PDX) models." (PMID 35900226, 2022). "Inhibition of CDK9 by selective inhibitors (e.g., AZ5576) or by genetic knockdown negatively regulated MYC and MCL-1 expression, and induced apoptosis in primary and transformed cells from this lymphoma, providing an attractive therapeutic strategy." (PMID 34041038, 2021). "In this study, we explored the anti-tumor effects of the GSK-3β inhibitor, 9-ING-41, in lymphoma cell lines as a single agent and in combination with novel agents comprising BCL-2 inhibitor (Venetoclax), CDK-9 inhibitor (BAY-1143572) and p110δ-PI3K inhibitor (Idelalisib)." (PMID 29383130, 2017).
cardiac hypertrophy (24 papers, 2012 to 2025). "The dysregulation of CDK9 activity or expression has been shown to be associated with several diseases, including cancer, cardiac hypertrophy, and acquired immunodeficiency syndrome (AIDS)." (PMID 35088192, 2023). "For example, P-TEFb is an essential cellular co-factor required for transcription and replication of the human immunodeficiency virus (HIV), and misregulation of CDK9 activity is associated with cardiac hypertrophy and cancer development." (PMID 34146121, 2021). "For instance, CDK9 is specifically targeted to cardiac hypertrophy-responsive promoters through association with important regulators of cardiomyocytes proliferation such as GATA4 and MEF2." (PMID 34146121, 2021). "Studies in mouse myocardium have shown that induction of Cdk9/cyclin T1 or Cdk7/cyclin H activity is linked to cardiac hypertrophy." (PMID 27270731, 2016). "Interestingly, we describe here a cardiac hypertrophy phenotype in Dnmt2-deficient mice independent from Cdk9 locus induction, mediated by the non-coding RNA Rn7sk." (PMID 27270731, 2016). "The Cdk9 mRNA is present in sperm, and injecting coding region fragments of the Cdk9 mRNA into mouse zygotes induced heritable cardiac hypertrophy." (PMID 40123230, 2025). "Flavopiridol is one of the most studied CDK9 inhibitors and has been tested in antitumor and cardiac hypertrophy clinical trials." (PMID 35088192, 2023). "Cyclin-dependent kinase 9 (CDK9), a kinase of positive transcription elongation factor, is an important validated target for the treatment of diseases, including cardiac hypertrophy, cancer and human immunodeficiency virus." (PMID 37225408, 2023). "CDK9 isa kinase involved in cardiac hypertrophy, which suggests that abemaciclibpossesses cardioprotective properties." (PMID 39076428, 2023). "For example, microinjection of either twenty nt fragments homologous to the coding sequence of the cell-cycle regulator Cdk9 or sense miR-1, which targets Cdk9, into zygotes were shown to produce animals with cardiac hypertrophy." (PMID 35466187, 2022). "The activity of the P-TEFb complex, a key driver for transcription formed by CDK9 and cyclin T, is increased in cardiac hypertrophy in mammals." (PMID 27812722, 2017). "Equally interesting is another downregulated lncRNA, the cyclin kinase Cdk9 inhibitor 7SK, which has been recently demonstrated to be involved in cardiac hypertrophy." (PMID 27317124, 2016). "We have shown previously that transcriptional induction of Cdk9 following small non-coding RNAs (sncRNAs) injection into one-cell embryos results in cardiac hypertrophy in mice." (PMID 27270731, 2016). "The proposed mode of therapeutic action of CDK9 inhibitors in cardiac hypertrophy is inhibition of RNA and protein synthesis by limiting gene transcription." (PMID 26542022, 2015). "Previous work has demonstrated that a dominant-negative CDK9 construct blocks ET-1-induced hypertrophy in cultured mouse cardiomyocytes, confirming a key role for the protein in cardiac hypertrophy." (PMID 26542022, 2015). "It has been shown that miR-1 down-regulation is necessary for the upregulation of CDK9, suggesting that the balance between miR-1 and CDK9 (i.e., P-TEFb) plays essential role during cardiac hypertrophy." (PMID 24701579, 2014). "Although the Jak/STAT pathway has been involved in the release and activation of P-TEFb in the context of cardiac hypertrophy, a miR-1-dependent regulation of CDK9 synthesis during cardiac differentiation and hypertrophy has been recently identified." (PMID 24701579, 2014). "It was reported that long-term overexposure to CDK9 may result in pathological cardiac hypertrophy; thus, CDK9 inhibitors have been investigated as new targets for treating hypertrophic cardiomyopathy." (PMID 36082129, 2022). "In addition, cardiomyocyte-specific transgenic overexpression of Cyclin-T1, a key component of the CDK9-activating complex, was sufficient to drive pathological cardiac hypertrophy in mice in vivo." (PMID 35896549, 2022).
cardiac hypertrophy (continued). "Similarly, RNAi-mediated inactivation of 7SK RNA in cardiomyocytes induces CDK9 activation and abnormal cell growth, and mice overexpressing Cyclin T1 also exhibit cardiac hypertrophy." (PMID 34146121, 2021). "By developing CDK9 targeted therapies, cardiac hypertrophy or even long term heart diseases could be treated effectively." (PMID 33805800, 2021). "Cdk is a cell-cycle check point regulator, and one study showed Cdk9 may have transcriptional roles in cardiac hypertrophy and mitochondrial dysfunction." (PMID 28882114, 2017). "Furthermore, the muscle-specific microRNA-1 (miR-1), which normally keeps CDK9 derepressed at the transcriptional level, was downregulated at a very early stage, following cardiac hypertrophy induced in a mouse model of aortic constriction-induced hypertrophy." (PMID 27812722, 2017). "Cdk9 paramutant animals displayed a hereditary cardiac hypertrophy." (PMID 27270731, 2016). "It is of note that production of oligoribonucleotides homologous to CDK9 mRNA in miR-1 microinjected one-cell embryo, as well as of miR-1 itself, determines the hyper-activation of CDK9 transcription and the establishment of cardiac hypertrophy in developed mice." (PMID 24701579, 2014). "Moreover, dysfunctions in the CDK9-related pathway are related with several forms of human tumors and cardiac hypertrophy." (PMID 23840966, 2013). "Targeting CDK9 with small molecule inhibitors represents a viable strategy for the treatment of several diseases, indicated especially by the deregulation of CDK9 activity in cancers, cardiac hypertrophy, HIV infections and pathological inflammation." (PMID 22571657, 2012). "These seminal findings suggested a role for the CDK9/PTEF-b transcriptional complex in cardiac hypertrophy, although the therapeutic potential of Pol II kinase inhibition could not be assessed due to lack of potent and specific chemical probes that were suitable for in vivo administration." (PMID 35896549, 2022). "Thus, the elucidation of the CDK9 pathway deregulations may provide useful insights into the pathogenesis and progression of human malignancies, cardiac hypertrophy, AIDS and other viral-related maladies." (PMID 23840966, 2013). "Cyclin-dependent kinase 9 (CDK9) is the most representative member of the CDKs family and plays an essential role in the development and progression of cardiac hypertrophy." (PMID 36082129, 2022). "The essential knowledge of the functional and structural biology of CDK9 allows to evaluate how and why the suppression of this enzyme can be beneficial in the fight against cancer, AIDS, cardiac hypertrophy, and perhaps even inflammation." (PMID 33805800, 2021). "Indeed, although pharmacological CDK9 inhibition has been proposed as a therapy for abrogating cardiac hypertrophy, the possibility of enhancing CDK9 activity has been overlooked as a mechanism that could be used to induce cardiac hypertrophy and to stimulate cardiomyocyte proliferation." (PMID 26542022, 2015). "CDK9 inhibition has been studied as a potential therapeutic target for multiple pathologies, including, AIDS, cardiac hypertrophy, inflammation and cancer." (PMID 24886624, 2014). "Nevertheless, there is a preference to consider CDK9 only as the more important enzyme due to the fact that dominant-negative form of CDK9 was effective in blocking cardiac hypertrophy, whereas dominant-negative form CDK7 was not." (PMID 33805800, 2021). "In addition, the roles of CDK9 in acquired immunodeficiency syndrome (AIDS) and cardiac hypertrophy have been reported." (PMID 26636538, 2016).
prostate carcinoma (23 papers, 2013 to 2025). A carcinoma that arises from epithelial cells of the prostate gland. "CDK9 gene amplification occurs frequently in prostate cancer, particularly CRPC, and is associated with increased levels of this kinase." (PMID 40163908, 2025). "Another observation reflecting the intimate association between BRD4, CDK9 and AR in prostate cancer is that cells that have acquired resistance to BRD4 inhibition exhibit adaptive responses to AR and CDK9." (PMID 40163908, 2025). "Our evaluation of CDK9 expression in clinical prostate tissues supports this concept in a prostate cancer context: more specifically, we found that CDK9 expression is associated with tumor grade and is predictive of disease recurrence following surgery." (PMID 39117800, 2024). "Moreover, high CDK9 expression was associated with poor prognosis of prostate cancer patients." (PMID 35394046, 2022). "The influence of CDK9 on AR pSer81 has been shown in both castration-sensitive and castration-resistant cell lines models of prostate cancer [,107]." (PMID 40163908, 2025). "CDK9 inhibition reduces aggressive prostate cancer cell growth by disrupting transcriptional elongation and AR-driven oncogenic programs and inhibits in vivo tumour growth." (PMID 40163908, 2025). "Recently, a study reported reduced migration and invasion of different prostate cancer cell lines in response to two other CDK8/CDK9 inhibitors, CCT251545 and G02788177.93–1 [,196]." (PMID 40163908, 2025). "KB-0742 is another orally bioavailable selective CDK9 inhibitor that has shown promising activity against prostate cancer." (PMID 40163908, 2025). "To measure the global effects of CDK9 inhibition on transcription in prostate cancer, we undertook RNA sequencing in LNCaP cells treated with CDKI-73." (PMID 39117800, 2024). "In this study, we highlight the relevance of CDK9 in promoting the growth and survival of aggressive prostate cancer and reveal the potential therapeutic utility of a CDK9 inhibitor, CDKI-73." (PMID 39117800, 2024). "Given the emerging evidence for CDK9’s cancer-promoting activity and its over-expression in prostate cancer, we investigated the therapeutic utility of an orally deliverable CDK9 inhibitor, CDKI-73." (PMID 39117800, 2024). "In summary, CDK9 is highly expressed in prostate cancer, particularly tumors with aggressive phenotypes, reinforcing its potential relevance as a therapeutic target." (PMID 39117800, 2024). "To garner evidence for CDK9 as a therapeutic target in prostate cancer, we assessed its expression in clinical transcriptomic datasets." (PMID 39117800, 2024). "Collectively, these pharmacodynamic analyzes confirm that CDKI-73 can inhibit the activity of CDK9 in prostate cancer cells." (PMID 39117800, 2024). "Overall, our study strongly supports the pursuit of CDK9 as a therapeutic target in prostate cancer, particularly in aggressive, therapy-resistant disease contexts." (PMID 39117800, 2024). "We used pantothenic acid in combination with CDK9 inhibitor to establish if this combinatorial strategy induces antiproliferative effects on prostate cancer cells." (PMID 35708495, 2022). "In our experiments, we noted that co-treatment of prostate cancer cells with vitamin B5 and CDK9 inhibitor induces combinatorial antiproliferative effects and further increased DNA damage, which were associated with decreased OGT expression." (PMID 35708495, 2022). "By identifying the proteins that are increasingly O-GlcNAcylated in response to CDK9 inhibition, we can establish mechanistically, why combined inhibition of OGT and CDK9 is toxic to prostate cancer cells." (PMID 35164752, 2022). "NEAT1 serves as a bridge to facilitate the binding between the major regulatory transcriptional kinase cyclin-dependent kinase 9 (CDK9) and its regulatory subunit cyclin L1 in prostate cancer cells." (PMID 35457249, 2022).
prostate carcinoma (continued). "In this study, we have employed a multiomics approach to understand how prostate cancer cells rewire transcriptional, proteomic, and metabolic networks when CDK9 and OGT are inhibited." (PMID 35708495, 2022). "Since MED1 phosphorylation is significantly increased during prostate cancer progression, we proposed that pharmacological inhibition of CDK9 can block MED1 phosphorylation, transcription recycling and CRPC growth." (PMID 35394046, 2022). "In conclusion, we have shown that OGT is required for the pro-survival metabolic rewiring of prostate cancer cells treated with CDK9 inhibitor." (PMID 35708495, 2022). "Co-targeting of O-GlcNAc transferase (OGT) and the transcriptional kinase cyclin-dependent kinase 9 (CDK9) is toxic to prostate cancer cells." (PMID 35708495, 2022). "Kronos Bio’s recently discovered KB-0742, a well-tolerated, orally bioavailable CDK9 inhibitor, significantly reduces tumour burden in models of prostate cancer in vivo." (PMID 35568739, 2022). "The data generated using the Seahorse system showed that the ability of prostate cancer cells to generate ATP was severely compromised when both CDK9 and OGT were inhibited." (PMID 35708495, 2022). "Combining pantothenic acid with CDK9 inhibitor significantly, albeit modestly, decreased the proliferation of prostate cancer cells (5%–10% decline)." (PMID 35708495, 2022). "We have shown that combined inhibition of OGT and CDK9 is toxic to prostate cancer cells, and here we used a multiomics approach to explain the mechanistic basis for the combinatorial effects." (PMID 35708495, 2022). "The starting point for our study was the combinatorial lethality screen, which discovered that co-targeting of OGT and CDK9 is toxic to prostate cancer cells; our goal in this project was to understand why this is." (PMID 35708495, 2022). "We performed an unbiased combinatorial lethality screen, which revealed that combined inhibition of OGT and cyclin-dependent kinase 9 (CDK9) is selectively toxic to prostate cancer cells." (PMID 35164752, 2022). "Here, we report a comprehensive glycoproteomic profiling of prostate cancer cells treated with CDK9 inhibitor." (PMID 35164752, 2022). "pS81 is co‐stimulated by CDK1 and CDK9, both representing potential therapeutic targets in castration‐resistant prostate cancer patients, either alone or in conjunction with direct AR antagonists." (PMID 33932081, 2021). "CDK9 inhibition promotes prostate cancer cells switch to fatty acid oxidation by inducing metabolic stress." (PMID 33748130, 2021). "This study was conducted on human glioblastoma and human prostate cancer cell lines and utilized siRNA molecules for the silencing of CDK9- and/or CDK7-related pathways." (PMID 23840966, 2013). "One prominent example is the expression of genes encoding the BCL-2 family of anti-apoptotic proteins – BCL2, MCL1 and XIAP – which is enhanced by CDK9 activity and thereby enables cancer cell survival in a wide range of tumour types, including prostate cancer [,87]." (PMID 40163908, 2025). "The oncogenic functions of CDK7 and CDK9 in prostate cancer are multifaceted." (PMID 40163908, 2025). "Inhibition of CDK9 results in an OGT-dependent remodeling of the proteome in prostate cancer cells." (PMID 35164752, 2022). "Indeed, treatment of prostate cancer cells with the highly specific CDK9 inhibitor NVP2, or a structurally unrelated CDK9 inhibitor AT7519, induced accumulation of the DNA damage response marker p-H2AX." (PMID 35164752, 2022). "Importantly, MED1 phosphorylation increases during prostate cancer progression to the lethal phase, and pharmacological inhibition of CDK9 decreases prostate tumor growth by decreasing MED1 phosphorylation and Pol II recycling." (PMID 35394046, 2022).